APC2 (APC regulator of Wnt signaling pathway 2)
Description:
Stabilizes microtubules and may regulate actin fiber dynamics through the activation of Rho family GTPases. May also function in Wnt signaling by promoting the rapid degradation of CTNNB1.
Synonyms: APCL; MRT74
Tractability: PROTAC: its protein half-life has been measured.
Gene: Protein-coding gene on chromosome 19 (1,446,302 to 1,473,244, forward strand). Ensembl gene ENSG00000115266.
Subcellular location: Cytoplasm, cytoskeleton; Golgi apparatus; Cytoplasm; Cytoplasm, perinuclear region
Subcellular location (Human Protein Atlas): Cytokinetic bridge; Cytosol; Midbody; Primary cilium
Gene Ontology:
Molecular function: beta-catenin binding; protein binding; gamma-catenin binding; microtubule binding
Biological process: activation of GTPase activity; microtubule cytoskeleton organization; negative regulation of canonical Wnt signaling pathway; cell fate specification; cell migration; negative regulation of microtubule depolymerization; nervous system development; pattern specification process; proteasome-mediated ubiquitin-dependent protein catabolic process; negative regulation of Wnt signaling pathway; Wnt signaling pathway
Cellular component: actin filament; catenin complex; cytoplasm; cytoplasmic microtubule; cytosol; filamentous actin; Golgi apparatus; intercellular bridge; lamellipodium membrane; microtubule cytoskeleton; perinuclear region of cytoplasm; beta-catenin destruction complex; cytoskeleton; leading edge membrane; plasma membrane bounded cell projection
Genetic constraint (gnomAD): Loss-of-function variants: 42 observed, 56.53 expected, observed/expected ratio (o/e) 0.74, 90% interval 0.58 to 0.96. The synonymous counts are far from expectation, so gnomAD's model fits this gene poorly and the ratio says little. Missense variants: 3,725 observed, 2,717.2 expected, observed/expected ratio (o/e) 1.37, 90% interval 1.33 to 1.41. Synonymous variants: 1,895 observed, 1,275.2 expected, observed/expected ratio (o/e) 1.49, 90% interval 1.43 to 1.54.
Gene-disease validity (ClinGen):
ClinGen rates the evidence that APC2 causes each of these diseases.
lissencephaly spectrum disorders (autosomal recessive): Strong.
Homologues: Orthologues: chimpanzee APC2 (99% identical), macaque APC2 (97% identical), pig APC2 (84% identical), rat Apc2 (82% identical), mouse Apc2 (81% identical), dog APC2 (81% identical), guinea pig APC2 (76% identical), tropical clawed frog apc2 (50% identical), zebrafish apc2 (41% identical), Drosophila melanogaster Apc (22% identical), Drosophila melanogaster Apc2 (14% identical), Caenorhabditis elegans apr-1 (12% identical). Paralogues in human: APC (38% identical).
Diseases named in the same sentence as APC2 in open-access papers:
APC2 is named in the same sentence as 71 diseases in open-access papers, as found by Europe PMC text mining. Sharing a sentence is not in itself a finding about the gene and the disease. The quoted sentences say what the papers report.
colorectal cancer (14 papers, 2013 to 2025). A primary or metastatic malignant neoplasm that affects the colon or rectum. "Interrogation of KEGG disease and DiSgeNET databases revealed an association between APC2 gene and colorectal cancer, medulloblastoma and breast cancer, while POU5F1 was mainly associated with germ cell tumors." (PMID 33503040, 2021). "For instance, in colorectal cancer, hsa-miR-663b promotes tumor cell proliferation and migration by targeting APC2 and activating the Wnt/β-catenin signaling pathway." (PMID 40724871, 2025). "In vivo and in vitro experiments showed that FOXO4 inhibited EMT, migration, and in vivo metastasis of colorectal cancer cells by regulating the APC2/β-catenin axis." (PMID 34631691, 2021). "In short, both FOXO4 and APC2 were downregulated significantly in colorectal cancer compared with a standard control, with a positive correlation." (PMID 34631691, 2021). "We observed the effects of FOXO4 overexpression and APC2 knockdown on the migration of colorectal cancer cells by wound-healing assays." (PMID 34631691, 2021). "Currently, there are no relevant findings on the diagnostic and prognostic roles of adenomatous polyposis coli 2 (APC2) in colorectal cancer (CRC)." (PMID 32951505, 2020). "This has not been possible, either with respect to the large puncta observed after overexpression in colorectal cancer cells, or the presumably smaller complexes produced when Axin and APC2 are expressed at endogenous levels." (PMID 29641560, 2018). "As a transcription factor, the FOXO4 expression was closely positively correlated with APC2 in colorectal cancer, which suggested that FOXO4 may bind the APC2 sequence and regulate its expression." (PMID 34631691, 2021). "Finally, we found APC2 was upregulated at the mRNA and protein levels in colorectal cancer cell lines (SW620 and HCT116) with FOXO4 overexpression (OE) for 48 h, and these similar results were verified by luciferase assay." (PMID 34631691, 2021). "APC2 was found to be a potential biomarker for colorectal cancer." (PMID 32951505, 2020). "Both siRNAs could significantly reduce the expression of APC2 in colorectal cancer cell lines." (PMID 34631691, 2021). "While this offered insights into the assembly ability of Axin and APC2, it involved very significant overexpression in an APC mutant colorectal cancer cell line." (PMID 29641560, 2018). "Similarly, in colorectal cancer (CRC), FOXO4 overexpression curtails cell migration and metastasis through reinforcement of the APC2/β‐catenin signaling axis." (PMID 41438489, 2025). "While some studies have reported its upregulation in breast and colorectal cancers, suggesting a potential oncogenic function, others have reported its downregulation in glioma, where it acts as a tumor suppressor by targeting oncogenes such as CORO2A, APC2, WNT7A, and BOC." (PMID 40431607, 2025).
lung carcinoma (7 papers, 2018 to 2023). "This protein functions as a tumor suppressor in different cancer types, including prostate, colorectal, and lung cancers, osteosarcoma, retinoblastoma, and glioma, where the APC2 gene expression was frequently found to be inhibited by hypermethylation." (PMID 32156068, 2020). "We have previously shown that APC2 promoter was methylated in control, whereas it was hypomethylated in lung cancer cell lines (H1299) that was treated with UNC0642." (PMID 32552834, 2020). "Thus, the low expression of APC2 and the increase of miR-4326 in lung cancer cell proliferation confirm that miR-4326 stimulates cell proliferation by inhibiting APC2." (PMID 35406675, 2022). "Inhibition of APC2 expression has been shown to inhibit proliferation of lung cancer cells." (PMID 32951505, 2020). "Interestingly, APC2 is the most frequently inactivated tumor suppressor by promoter methylation in lung cancer." (PMID 30348169, 2018). "Notably, APC2 is frequently inactivated by promoter methylation in lung cancer." (PMID 30348169, 2018). "In lung carcinoma, G9A participates in the activation of WNT signaling by suppressing relating inhibitors like APC2, DKK1, and WIFI, which ultimately promotes cell proliferation." (PMID 37739945, 2023).
ovarian carcinoma (7 papers, 2003 to 2024). A malignant neoplasm originating from the surface ovarian epithelium. "In ovarian cancer, miR-939 was demonstrated to promote tumor proliferation by repressing the expression of adenomatous polyposis coli 2 (APC2)." (PMID 38420020, 2024). "In ovarian cancer, miR-939 dramatically promoted ES-2 cell proliferation by suppressing APC2 expression." (PMID 29228624, 2017). "The recently found APC-like gene, APC2, which presented with allelic imbalance in 19 out of 20 ovarian cancers, is also noteworthy." (PMID 14520463, 2003). "In ovarian cancer, APC2 has been reported to be involved in miRNA-mediated tumor growth inhibition." (PMID 32951505, 2020). "APC2 was repressed by miR-939 through the Wnt/β-catenin pathway in ovarian cancer." (PMID 30510602, 2018). "In ovarian cancer, miR-939 plays an important role in the progression and regulation of cell growth and cell cycle; it has been demonstrated that ES-2 cells transfected with miR-939 mimic show APC2 decreased expression, suggesting that APC2 may be a target of miR-939." (PMID 26772808, 2016). "Its homologue gene, APC2/APCL, located on chromosome 19p13.3, plays a significant role in several human cancers, including retinoblastoma (RB) tumor, lymphocytic leukemia, and ovarian cancer." (PMID 30510602, 2018).
breast carcinoma (6 papers, 2017 to 2023). "Next, we asked whether concurrent loss of APC and APC2 was breast cancer subtype specific and detected an enrichment of dual loss for triple-negative breast cancers (Fisher’s exact test two tailed P<0.0001 in both data sets)." (PMID 27694902, 2017). "Inhibition of APC2 expression results in increased sensitivity of breast cancer cells to Panobinostat treatment." (PMID 32951505, 2020). "The results showed that mRNA and protein levels of these target genes, especially APC2, were significantly elevated in glioblastoma and breast cancer cell lines after treatment with 40μM AQB." (PMID 31367244, 2019). "To interrogate overall survival of breast cancer patients with concurrent APC and APC2 loss, we performed Kaplan–Meier survival analyses in the METABRIC breast cancer cohort." (PMID 27694902, 2017). "To address the relevance of APC and APC2 in human breast cancer, we interrogated primary invasive ductal carcinomas from the publically available METABRIC54 and TCGA BRCA55 cohorts." (PMID 27694902, 2017). "In the 965 TCGA breast cancer samples, the genomic APC regions was lost in 108 samples (11.3%), APC2 in 91 (9.5%) and concurrent loss of APC and APC2 was seen in 35 (3.7%) of samples." (PMID 27694902, 2017). "APC2, as one of the target genes, was significantly up-regulated by AQB and led to degradation of β-catenin resulting in suppression of Wnt/β-catenin signaling which may contribute to inhibition of tumor growth and metastasis in vitro and in orthotopic breast cancer models." (PMID 31367244, 2019).
colon cancer (5 papers, 2012 to 2023). "By suppressing Wnt signaling inhibitor APC2, overexpression of hsa‐miR‐11,181‐3p can promote Wnt signaling pathway and increase cell viability in colon malignant tumor cell line." (PMID 36911092, 2023). "The development of CRISPR knockout technology will allow future examination of the importance of truncated APC1, as well as the endogenous APC2 and Axin expressed in colon cancer cells in destruction complex assembly and function." (PMID 26393419, 2015). "Our experiments show for the first time that colon cancer cells express a functional APCL (or APC2) that controls the level and/or the transcriptional activity of β-catenin." (PMID 23840886, 2013). "We show here that colon cancer cell lines express also the paralog APC-like (APCL or APC2)." (PMID 23840886, 2013). "Since N-terminally truncated fragments of human APC can rescue ßcat degradation in human colon cancer cells, it is not inconceivable that APC233 or even APC219–33 might encode very low levels of an N-terminally truncated APC2 protein that nonetheless retained some function in Wnt regulation." (PMID 22359584, 2012).
glioma (4 papers, 2019 to 2025). A benign or malignant brain and spinal cord tumor that arises from glial cells (astrocytes, oligodendrocytes, ependymal cells). "The upregulation of miR-1249-3p promoted glioma cell proliferation by downregulating the expression of a key regulator of the Wnt/β-catenin signaling pathway, the adenomatous polyposis coli 2 (APC2)." (PMID 31769433, 2019).
brain tumors (3 papers, 2018 to 2024). "In this study, we report that Brain Tumor maintains Apc2 at the plus-ends of microtubules to promote axon elongation and midline crossing." (PMID 29617376, 2018).
breast tumors (3 papers, 2017 to 2021). "In addition, alterations in APC2 through loss of heterozygosity, promoter hypermethylation and somatic copy number aberrations were also described in breast tumors." (PMID 33503040, 2021). "From the 1381 primary breast tumors in METABRIC, loss (copy number <2) of APC, located on 5q22.2, was observed in 96 (6.9%) and loss of APC2 on 19p13.3 in 118 (8.5%)." (PMID 27694902, 2017).
dysplasia (3 papers, 2019 to 2026). A usually neoplastic transformation of the cell, associated with altered architectural tissue patterns. "For neoplastic mucosa a five marker panel (SFRP2, SFRP4, WIF1, APC1A, APC2) was accurate in detecting pre-cancerous and invasive neoplasia (AUC = 0.83; 95% CI: 0.79, 0.88), and dysplasia (AUC = 0.88; (0.84, 0.91)." (PMID 30473377, 2019). "The ENDCAP-C trial, a multicenter study to assess the role of molecular markers in improving the detection of dysplasia, identified the methylation of a five-marker panel (SFRP2, SFRP4, WIF1, APC1A, APC2) that accurately detected ulcerative colitis associated dysplasia." (PMID 41562706, 2026).
retinoblastoma (3 papers, 2018 to 2023). A malignant tumor that originates in the nuclear layer of the retina. "Apc2 was found hypermethylated in 70% of tumor samples, and as a result, Wnt is activated in retinoblastoma." (PMID 37667345, 2023). "The tumor suppressor role of Apc2 was also observed in retinoblastoma cell lines." (PMID 37667345, 2023).
Sotos syndrome (3 papers, 2018 to 2023). Sotos syndrome is a rare multisystemic genetic disorder characterized by a typical facial appearance, overgrowth of the body in early life with macrocephaly, and mild to severe intellectual disability. "In contrast to the Nsd1 mutant mice that does not show an enlarged head circumference, loss of function mutation in Apc2 resulted in a Sotos Syndrome-like phenotype in mice, with increased head circumference and dilated brain ventricles." (PMID 36845425, 2023). "In humans, mutations in Adenomatous Polyposis coli 2 (APC2), a protein with a crucial role in the control of neuronal migration and axon guidance, have been identified by whole exome sequencing as an additional cause of Sotos syndrome." (PMID 36845425, 2023). "One of NSD1′s potential downstream effectors in Sotos syndrome is Adenomatous polyposis coli 2 (APC2), a tumor suppressor gene involved in the negative regulation of the Wnt/β-catenin signaling pathway." (PMID 36230787, 2022). "Sotos syndrome patients present with multiple neurological symptoms, including Autism Spectrum Disorder, which have in part been attributed to APC2’s role in neuronal development and function." (PMID 30018294, 2018). "It would be interesting to determine whether Apc2-knockout mice would represent a model to study Sotos syndrome." (PMID 36230787, 2022). "Furthermore, Apc2 knockout mice showed some phenotypic similarities to human Sotos syndrome, i.e., impaired learning and memory abilities, therefore there is a possibility that APC2 expression is repressed in patients with Sotos syndrome and could affect neuronal functions." (PMID 36230787, 2022).
thyroid cancer (3 papers, 2022 to 2025). "Another study in thyroid cancer cells showed that LSD1 directly regulates APC2 (adenomatous polyposis coli 2) and indirectly promotes the transcription of DKK1 (dikkopf-related protein 1) through HIF1α." (PMID 40028036, 2025). "In summary, KDM1A can upregulate the Wnt/β-catenin signaling pathway in thyroid cancer cells by suppressing the ubiquitin-proteasome degradation of β-catenin and its regulation on APC2 and DKK1 may contribute to this process." (PMID 35198054, 2022). "APC2 and DKK1 down-regulate β-catenin by enhancing ubiquitination levels to control the Wnt/β-catenin pathway, thereby promoting the progression of thyroid cancer and decreasing the sensitivity to chemotherapy." (PMID 40028036, 2025). "LSD1 can downregulate the Wnt pathway antagonists APC2 and DKK1 through demethylation in thyroid cancer, thus inhibiting APC2 transcription and activating the HIF-1α/DKK1 axis to regulate cancer progression." (PMID 36059955, 2022).
Alzheimer disease (2 papers, 2024). A progressive, neurodegenerative disease characterized by loss of function and death of nerve cells in several areas of the brain leading to loss of cognitive function such as memory and language. "A duplication of the APC Regulator of WNT Signaling Pathway 2 (APC2) gene has been found to be protective against developing Alzheimer disease with psychotic symptoms." (PMID 39367879, 2024). "The DEGs that were down-regulated in DM compared to NM were primarily related to the ribosome (about 23 DEGs, including RPL37A and RPS11), Alzheimer’s disease (about 19 DEGs, including APC2 and COX8A), and non-alcoholic fatty liver disease (about 11 DEGs, such as SNCA and COX8A)." (PMID 38660519, 2024).
cervical cancer (2 papers, 2022 to 2026). A primary or metastatic malignant neoplasm involving the cervix.
Familial adenomatous polyposis (2 papers, 2013 to 2018). Familial adenomatous polyposis (FAP) is characterized by the development of hundreds to thousands of adenomas in the rectum and colon during the second decade of life. "For instance, the functional complementation of APC2 constituted a substantial facet of tumor development for the retention of 15R to target β-catenin in familial adenomatous polyposis (FAP) patients." (PMID 30510602, 2018).
granulosa cell tumor (2 papers, 2019 to 2020). A slow-growing, malignant tumor, characterize by the presence of granulosa-like cells and Call-Exner bodies, that is almost always found in the ovary. "APC2 deficiency leads to susceptibility to granulosa cell tumor formation in mice and causes ovarian deficiency to promote tumor growth." (PMID 32951505, 2020). "APC2-deficiency in these mice resulted in predisposition to granulosa cell tumour (GCT) formation, accompanied by acute tumour-associated WNT-signalling activation and a histologic pattern and molecular signature seen in human adult GCTs." (PMID 31291912, 2019).
Obesity (2 papers, 2024 to 2025). Accumulation of substantial excess body fat. "Specifically in eWAT, there was an expansion of the APC4 proportion alongside a reduction in APC1 and APC2 populations during obesity, suggesting distinct tissue expansion mechanisms in each adipose tissue depot." (PMID 38645263, 2024).
ovarian tumor (2 papers, 2019 to 2020). "Not only does this study extend our understanding of the tissue-specific regulation of WNT signalling, but also the APC2-deficient mouse has excellent potential as a pre-clinical model to study ovarian tumour biology and for therapeutic testing." (PMID 31291912, 2019).
prostate carcinoma (2 papers, 2019 to 2022). A carcinoma that arises from epithelial cells of the prostate gland. "miR-3648 facilitates prostate cancer cell proliferation by inhibiting APC2, which leads to the activation of the Wnt/β-catenin pathway by increasing cyclin D1 and cyclin E1 expression and decreasing p21 expression." (PMID 35037826, 2022). "In contrast, by targeting EGLN3 and APC2, miR-1205 has an oncogenic role in castration-resistant prostate cancer and lung adenocarcinoma, respectively." (PMID 31801947, 2019).
adenoma (1 paper, 2015). A neoplasm arising from the epithelium. "In the current study, we observed increased methylation of APC2 and decreased methylation of SFRP2 in adenomas in Apcmin/+ mice." (PMID 26101583, 2015).
asthma (1 paper, 2018). "In our post hoc between-group analyses, APC1 and APC2 were similar to each other in terms of pulmonary function tests, questionnaire results, and other typical indicators of asthma severity than APC3 was to either APC1 or APC2." (PMID 30286807, 2018).